IL22 (interleukin 22)
Diseases named in the same sentence as IL22 in open-access papers (continued):
Sharing a sentence is not in itself a finding about the gene and the disease.
infection (continued). "However, we did not detect any differences in the production of IFN-y, IL-12, IL-22, IL-23, or IL-1β between the control and anti-Gr1 groups after 2 weeks of infection." (PMID 36776848, 2023). "In addition, although the transcription of various cytokines, such as IL-1β, IL-2, IL-4, IL-8, and IL-10, was shown to be highly upregulated to defend the organism against DHAV-(1/3) infection, the variation of duck IL-22 after DHAV infection is still unclear." (PMID 37391858, 2023). "In fact, LTi cells produce IL-22, IL-17A, and IL-17F as a result of RORγt expression and are involved in the creation of secondary lymphoid organs during embryogenesis and maturity, as well as in their restoration after infection." (PMID 37047071, 2023). "Despite these limitations, the present study was able to show that symptomatic P. falciparum infection is associated with increased levels of the cytokines IL-10, IL-13, IL-6, IFN-γ and IL-12p70 while asymptomatic infection is marked by increased levels of IL-10, IL-13, IL-22 and IL-12p70." (PMID 36787308, 2023). "IL-22 induced the production of CXCL1 chemokine to recruit neutrophils at the infection sites." (PMID 37403036, 2023). "According to studies on Th22 cells, Th22/IL-22 may be a promising therapeutic target and an effective treatment strategy for various infections." (PMID 36839448, 2023). "The protective effects of IL-2219 and the coincidence of increased cytokine production with BC expansion in airways and alveoli led us to speculate that IL-22 signaling plays a role in BC expansion following PR8 infection." (PMID 37726288, 2023). "Here, we reported that IL-22 expression was highly facilitated after DHAV-1 infection both in vitro and in vivo, and the increase in expression might be due to duck STAT3 directly antagonizing STAT1 and leading to an increase in IL-22 promoter activities." (PMID 37391858, 2023). "Interestingly, it was shown recently, that S. Typhimurium can exploit ILC3-derived IL-22 for its own benefit to promote the infection." (PMID 36430676, 2022). "During the early phase of the C. rodentium infection, VD is essential for the differentiation of ILC3 and the production of IL-22, which may be required for the normal expansion of Th17 cells during the later phase of infection." (PMID 35458125, 2022). "However, early in infection, the anti-inflammatory cytokines IL-10 and IL-22 were also locally and systemically upregulated in BaP-exposed S.E.-infected mice." (PMID 35203386, 2022). "Along this line, susceptibility to infections by enteric extracellular pathogens are increased in the absence of IL-22 or GM-CSF, highlighting a critical role for ILC3-associated cytokines in barrier defense." (PMID 35359972, 2022). "During early infections, IL-22 is primarily produced by ILCs and only later on by T cells." (PMID 36248804, 2022). "In this way, BaP-mediated upregulation of Il22 might also contribute to the limitation of local infection and the development of systemic inflammation as well." (PMID 35203386, 2022). "Furthermore, IL-22 signaling regulates chemokine expression to orchestrate the recruitment of immune cell subsets to sites of infection." (PMID 35777848, 2022). "The absence of IL-22 results in increased susceptibility to M. tuberculosis infection during the chronic stages of infection, but IL-22 is dispensable during the acute stages." (PMID 35363832, 2022). "When assessing neonatal cytokine levels in cord blood, most of the cytokines tested were mostly undetectable in samples from non-infected and infected mothers, except for IL-22, the production of which was significantly increased in neonates of patients with ongoing infection (p = 0.0497)." (PMID 35911747, 2022). "However, at 39 weeks post-infection, anti-IL-17A mAb treatment significantly enhanced lung IL-4 and IL-22 levels compared to isotype-matched control Ab treatment in the lungs of M. intracellulare-infected mice." (PMID 35363832, 2022).
infection (continued). "In contrast, by flow cytometry and immunofluorescence analyses of fresh “untouched” crypt samples for stem cells and TA cells, we found that loss of Il-22, epithelial Stat3, or Il-18 in mice indeed cause a reduction of Lgr5+ and Ki67+ crypts at the steady state and during AIEC infection." (PMID 35169117, 2022). "IL-22 contributes to lung epithelial repair following infection." (PMID 36305904, 2022). "Although the level quantified remained low, IL-22 production in cord blood samples from patients with ongoing infection was significantly correlated with the frequency of NK cells in neonates (r = −0.8047; p = 0.0043) and the production of estradiol (r = −0.6713; p = 0.0143)." (PMID 35911747, 2022). "Nevertheless, ILC3-derived IL-22 and LTα positively alter the glycosylation activity of epithelial cells, supporting glycan-scavenging intestinal commensal microbes and balanced host-microbe interactions and providing protection from infection." (PMID 35359972, 2022). "In addition, IECs can propagate the immune cell IL-22 response through secretion of chemoattractant resistin-like molecule-beta (RELM-β) that recruits IL-22 producing CD4+ T cells to the sites of infection." (PMID 36341403, 2022). "In addition to aiming at in-situ infection in the kidney, IL-22 significantly reduces the incidence of hematogenous dissemination after infection, possibly by inducing antimicrobial peptide expression in renal epithelial cells." (PMID 35432360, 2022). "In addition, several lung specific mechanisms responsible for weight loss during lung infection are under-investigation including the effects of IL-22 upregulation in infected lungs, alterations in gut microbiota post-infection, and decreased food intake." (PMID 35784337, 2022). "IL-17A and IL-22 are proinflammatory Th17 cell cytokines that synergize to promote neutrophil recruitment early after infection, and increase neutrophil bactericidal activity via enhanced production of defensins and calcium binding proteins, resulting in pathogen clearance." (PMID 36060742, 2022). "Indeed, IL-22 was required for M. tuberculosis control at the chronic stage of infection, whereas IL-17 was important in the acute stage of M. tuberculosis infection in the same mouse model." (PMID 35777848, 2022). "Consistent with an important role for IL22 in epithelial barrier repair in the bladder, we observed fewer Ki67-positive cells within the bladder epithelium in IL22ra1−/− mice at 24 h following infection as well as a reduction in Mki67 transcripts." (PMID 35845169, 2022). "It was reported that IL-22 could activate ILC3s indirectly by inducing epithelial IL-18 during infection and IL-25-expressing epithelial cells could suppress IL-22 production by ILC3s72,73." (PMID 34294718, 2021). "Ifnγ expression by Th22 subsets questioned whether SFB induces Th1 cells that are able to secret IL-22 upon infection." (PMID 34566952, 2021). "This might indicate that like in mammals, low levels of IL-22 are necessary to maintain homeostasis and increased levels might be necessary to combat infections." (PMID 34603258, 2021). "IL-22, produced by ILC3s, is essential in the early phase of infection." (PMID 34659248, 2021). "In conclusion, IL-17 from ILC3s potentiates the bacterial clearance of K. pneumoniae; furthermore, production of IL-22 by ILC3s could also help to control the infection." (PMID 34659248, 2021). "Indeed, we have shown administration of a neutralizing anti-ICOS antibody to mice prior to bacterial infection resulted in a decrease in Icos expression as well as expression of Il17 and Il22 after infection with Klebsiella pneumoniae." (PMID 33968082, 2021). "Further, these cells are early responders to infection through the production of IL-22." (PMID 34804991, 2021). "Especially the spreading of infections to neighboring cells appears to be blocked by IL22." (PMID 34045640, 2021). "Most studies examining IL-22 have focused on its role of the injured lung after infection." (PMID 34597299, 2021).
infection (continued). "In summary, the potential role for IL-22BP in the CNS is complicated, and further studies are warranted to determine whether IL-22 biology is a viable therapeutic target for inflammation and infection in this tissue." (PMID 34868019, 2021). "We next tested whether IL-22 can confer rotavirus resistance by treating Abx mice with recombinant IL-22 one day before and on days 0, 1, 2 and 4 after oral infection with rotavirus, then monitoring fecal virus shedding by ELISA for the next 12 days." (PMID 34383769, 2021). "Low levels of IL-22 early in life may pre-dispose certain sub-populations of CF patients to poorer immunological responses to infection, increased neutrophil recruitment and so contribute to greater lung damage later in life." (PMID 33869115, 2021). "Therefore, in a second experiment, the IL-22 treatment period was extended and daily injections of IL-22 were continued until day 8 post-infection." (PMID 34383769, 2021). "Interleukin-22 (IL-22) plays an integral component in recovery of the lung from infection." (PMID 34597299, 2021). "This revealed increased transcript levels of IL-22 in lymph ILCs after STM infection." (PMID 33414524, 2021). "While IL-22-deficient mice had no change in viral clearance, these same mice had dramatically impaired survival after S. pneumoniae secondary infection." (PMID 33968082, 2021). "This characteristic of IL-22 may act in synergy with its protective effects on IL-22R expressing tissue cells to reduce collateral damage in the context of infection and inflammation." (PMID 33692792, 2021). "However, IL-22 also plays a pivotal role in direct infections of the liver by many different bacteria, protozoa, helminths, and viruses." (PMID 33851257, 2021). "pneumoniae (ST258), the kinetics of the two cytokines are distinct, with expression of IFN-λ increasing steadily with infection, coincident with the arrival of recruited monocytes, while IL-22 increases briefly at the start of infection and then again in the resolution phase." (PMID 32637365, 2020). "- IL-22 is upregulated during infection of Flavobacterium columnare and grass carp reovirus." (PMID 33178219, 2020). "The proportion of IL-22 producing ILC3s was about 30% in the gut with the pathogen infections." (PMID 33377111, 2020). "Moreover, using 2 × 106 yeasts, IL-22 production was increased at the 7th day of infection in C57Bl/6 mice." (PMID 32517114, 2020). "Furthermore, rIFN-γ treatment reduced fungal load in the lungs of Il22−/− mice at seven days post-infection, as well as reduced NO2−." (PMID 32517114, 2020). "Moreover, the IL-22-positive cells were found to be induced in the hindgut and head kidney 24 h after infection by F. columnare." (PMID 33178219, 2020). "After C. albicans GI infection, the level of plasma IL-22 in Rag2γc mice remained significantly lower than the level as compared to that in B6 mice, although the level of IL-22 was slightly elevated in untreated Rag2γc mice 12 days after infection." (PMID 33488563, 2020). "In addition, it has been shown that STAT3 is essential for type 3 ILCs to produce IL-22 to protect intestinal tissues from infection in mice." (PMID 33329513, 2020). "Histological analyses of the lungs at 2, 7 and 14 days post-infection demonstrate that mice from both genotypes exhibited increased cellular infiltration over the course of infection, but Il22−/− animals presented greater lung inflammation 7 days after infection with H. capsulatum." (PMID 32517114, 2020). "Moreover, genes such as Ifr9, Ifr8, Ifr7, CSF2RA, STAT1, and STAT2 were expressed to a greater extent in the PmQ infection group than PmCQ2, and Il22, Il6, Nos2, Ccl4, Ccl5, Ifr1, Socs1, and Socs3 were increased only in PmQ infected chickens rather than PmCQ2." (PMID 32851030, 2020). "Therefore, in inflammatory conditions, like in tissue injury, or infection, IL-22 level is significantly enhanced." (PMID 33042126, 2020).
infection (continued). "Enhancing mucosal defenses by modulating the cytokines that regulate barrier functions, such as interleukin-22 (IL-22) and interferon-λ (IFN-λ), members of the IL-10 family of cytokines, is an attractive approach to prevent these infections that are associated with high morbidity and mortality." (PMID 32637365, 2020). "IL-22 pro-inflammatory response following HBV recognition by liver T cells might play beneficial role in infection." (PMID 33042126, 2020). "Interestingly, at 24 h post-infection, the Trivalent-FP induced IL-22-producing CD4+ T cells in the WT group as well, suggesting that the IL-22 production is not controlled by the human-FcγRI." (PMID 32340134, 2020). "This regulation may be bi-directional as IL-22–/– mice had decreased IFNλ expression in the later phases of infection." (PMID 32582219, 2020). "In addition, I3C treatment reduced the inflammatory response to Cr infection by maintaining anti-inflammatory cytokine IL-22 mRNA levels while reducing expression of other pro-inflammatory cytokines including IL17A, IL6, IL1β, TNF-α, and IFN-γ." (PMID 33076301, 2020). "The mice inoculated with EF3030 and active PIV contained by day 2 post-infection less than 50 pg/mL of IL-22 in the lung homogenate whereas lungs infected with EF3030 alone, EF3030 plus heat-inactivated PIV, or EF3030 plus LasB contained approximately three-fold more IL-22 (i.e., 120 to 170 pg/mL)." (PMID 31443433, 2019). "We therefore excluded the ΔnleA strain from infection-induced lethality in Il22-/- mice." (PMID 31251784, 2019). "Consistent with our above findings, infection with ΔespF CR caused minor body weight loss and no death in Il22-/- mice, even after 21–28 dpi." (PMID 31251784, 2019). "Thus, our results further underscore the requirement of EspF for the CR infection-induced mortality and morbidity in Il22-/- mice." (PMID 31251784, 2019). "We further examined whether CR infection triggers TJ disruption in the colon of infected Il22-/- animals." (PMID 31251784, 2019). "IL-22 production by ILC3 in response to IL-23 is essential for host defense against pathogenic bacteria such as C. rodentium, whereas ILC3 was involved in the IL-23-driven intestinal pathology during infection with Helicobacter hepaticus." (PMID 30753547, 2019). "Similarly, the antimicrobial factor Reg3γ was increased during infection, as was the multifunctional cytokine IL-22." (PMID 31848276, 2019). "Furthermore, IL-22 transcript levels were also significantly increased in the gill samples after infection." (PMID 31306696, 2019). "IL-22 secreting ILC3s were higher in D+ than D- colon before and after infection." (PMID 30723466, 2019). "In addition to these findings, our study demonstrates for the first time that IL-22 and LTi cells prevent epithelial cell damage to inhibit infection-induced inflammation in a T2DM host." (PMID 31809521, 2019). "Moreover, we orally administrated FITC-dextran to the infected Il22-/- mice at the peak of infection and assessed colonic barrier function by measuring translocated FITC-dextran in serum." (PMID 31251784, 2019). "The persistent defects in mucosal immunity may fuel peripheral T-cell abnormalities through diverse mechanisms, including the production of IL-17/IL-22, cellular permissiveness to infection and regulation of T-lymphocyte maturation." (PMID 30763359, 2019). "The peak of IL-18 production in the initial phase of infection was not affected in mice deficient of IL-22." (PMID 31681274, 2019). "Hence these results suggest that many virulence genes encoding TJ-disrupting effectors are upregulated in general, in line with the severe damage to colonic epithelial barrier integrity, during CR infection in Il22-/- animals." (PMID 31251784, 2019). "Here, the levels of IL-4, IL-6, and IL-22 showed a similar trend during the infection period, indicating they might help to balance inflammatory reactions." (PMID 31711531, 2019).
infection (continued). "Given the observed severe tissue damage in the colon derived from wild-type CR-infected Il22-/- mice, we monitored bacterial load in the peripheral organs of infected animals at the peak of infection, to assess the impact of EspF on the translocation of CR through the damaged colonic epithelium." (PMID 31251784, 2019). "T cells that made IL-17 and IL-22 were higher in the D+ vs. D- colon following infection." (PMID 30723466, 2019). "Th17 cells and IL-22 production by ILC3 are important to prevent infection by C. rodentium." (PMID 31555282, 2019). "Furthermore, the D+ WT and D-WT mice that received IL-22 Fc cleared the infection by d35 when the D- WT isotype treated mice still had 2 logs of C. rodentium in the feces." (PMID 30723466, 2019). "IL-22 is produced by innate class 3 lymphoid cells (ILC3s) during the establishment and expansion phases of infection, followed by CD11b+ Ly6C+ Ly6G+ neutrophils and Th17 and Th22 T cells, which contribute to IL-22 production during the steady-state and clearance phases." (PMID 30940698, 2019). "Upon infection, epithelia exhibit defense mechanisms such as increasing mucus flow, tightening the packing of cells, migration to the surface and increasing proliferation (promoted by Interleukin-22 cytokines)." (PMID 30673699, 2019). "Interestingly, Nlrc4−/− mice phenocopied Il22−/− mice as IL-18 levels were unaffected in the early phase of the infection but dramatically reduced in the later phase, consistent with previous findings showing that IL-22 and NLRC4 works along the same pathway." (PMID 31681274, 2019). "IL-22 is a cytokine that is expressed by a number of immune cell types and acts on the epithelium to induce proliferation and growth, making it an extremely vital player in mediating repair following infection." (PMID 29988424, 2018). "Upregulation of the IL-22R1 in infected macrophages may be a host-mechanism to combat the infection, as there is growing evidence that IL-22 can modulate mycobacterial growth within macrophages." (PMID 30319650, 2018). "In this review, we hypothesise that IL‐22 has a primary role in tissue restitution following clearance of infection and damaged cellular debris from any injury." (PMID 29713472, 2018). "Expression of colonic IL-22 is induced under inflammatory conditions such as infection and IBD." (PMID 30365535, 2018). "A study based on a high fat diet mouse model of T2D showed that the induction of IL-22 from CD4+ cells is impaired in obese mice in response to challenge with the intestinal pathogen Citrobacter rodentium, making them more susceptible to infection." (PMID 30319650, 2018). "Also, IL-22 has been related to protective functions in epithelia through a regenerative action on injured epithelia after infection." (PMID 29621276, 2018). "How to reconcile these pro‐inflammatory outcomes with the hypothesis that IL‐22 is involved in restitution after clearance of infection and damaged cells?" (PMID 29713472, 2018). "Activation of the IL-22 signaling pathway in epithelial cells results in epithelial tissue proliferation, regeneration, and healing, therefore this cytokine plays an important role in protection from infection-induced tissue damage at mucosal surfaces." (PMID 30319650, 2018). "In the absence of HIC1, group 3 ILCs (ILC3s) that produce IL-22 are lost, resulting in increased susceptibility to infection with the bacterial pathogen Citrobacter rodentium." (PMID 29470558, 2018). "Using the direct ICS approach, we found that macaques infected with MDR-Mtb exhibited more substantial increases in T effector cells constitutively producing IFN-γ, perforin, IL-17, and IL-22 in the blood at week 3 after infection when compared with the Erdman-infected animals." (PMID 30538219, 2018). "Collectively, it is demonstrated here that LP enhanced IL-22 production in NK cells that might be able to protect the integrity of intestinal epithelial barrier despite infection with ETEC K88." (PMID 29137183, 2017).